INS (insulin)
Diseases named in the same sentence as INS in open-access papers (continued):
Sharing a sentence is not in itself a finding about the gene and the disease.
Hyperinsulinemia (continued). "Therefore, the antioxidant effects of NAC may act as a therapeutic approach to improve the level of circulating insulin as well as insulin sensitivity in PCOS patients with hyperinsulinemia." (PMID 28367412, 2017). "Encouraging by the clues from two genetic diseases, PCOS and CAH, in which hyperandrogenism and hyperinsulinemia are simultaneously co-existed, therefore we attempted to test whether the T play a role for the pancreatic progenitor cell differentiating to insulin-producing cells." (PMID 28594910, 2017). "It has been proposed that inflammatory cytokines secreted by adipose tissue of insulin resistant patients as well as hyperinsulinemia itself may negatively modulate the expression of sodium/iodine symporter (NIS) on the apical surface of enterocytes, thus inducing a decrease in iodine absorption." (PMID 29184536, 2017). "The reasons for the hyperinsulinemia during HS are not clearly understood, but may include the key role of insulin in activating and up-regulating HSPs, which are important mediators of insulin action and sensitivity." (PMID 27904969, 2017). "Despite the results of these epidemiological studies establish hyperinsulinemia as an independent predictor of cardiovascular outcomes, it could not provide the biological explanation between high insulin level and CVD risk." (PMID 28529547, 2017). "Therefore, we believe that therapeutic strategies focusing on increased IDE expression and insulin clearance could be helpful in the prevention and/or treatment of T2D, especially when hyperinsulinemia precedes the development of this pathology." (PMID 29093479, 2017). "The observation that maternal exercise prevented an increase in placental lipid deposition in parallel with a reduction in maternal insulin levels suggests that hyperinsulinemia and therefore increased insulin action on the placenta may contribute to the increased placental lipid deposition." (PMID 28291256, 2017). "Additionally, it is well known that once insulin treatment is established, adequate levels of portal insulin are obtained at the expense of peripheral hyperinsulinemia, which may have an impact on various organs and tissues (e.g., bone)." (PMID 28630427, 2017). "In addition, the improvement in hyperinsulinemia and insulin sensitivity in HyO DJB rats, may also be involved in such process." (PMID 28380195, 2017). "However, upon weight augmentation by aging or diet challenge (30 weeks old), the Bif-1 KO mice showed hyperinsulinemia and similar circulating glucose levels compared to the WT mice (data not shown), indicating that the obese Bif-1 KO mice had lower insulin sensitivity." (PMID 26857140, 2016). "However, due to the fact that conventional insulin assay has cross-reactivity with proinsulin, there is a debate as to whether hyperinsulinemia or hyperproinsulinemia exists in newly diagnosed T2DM." (PMID 27746815, 2016). "In contrast, the HF/HF mice show hyperinsulinemia in both the day and the night, highlighting marked changes in circadian physiology following developmental HF exposure, and suggesting that these offspring are insulin resistant, a known factor in the pathogenesis of fatty liver disease." (PMID 27040510, 2016). "Since DIO mice may develop hyperinsulinemia, we assayed the serum insulin levels of mice." (PMID 27088095, 2016). "More recently, it was demonstrated that rodents, mainly rats, treated with DEX (1 mg/kg b.w. for 5 days) have reduced insulin clearance and lower hepatic activity of insulin-degrading enzyme, which may also corroborate for the hyperinsulinemia in these animals." (PMID 27527232, 2016). "The impact of serum cholesterol on insulin exocytosis was further assessed in diet induced hypercholesterolemic animal model, where rodents on short term feeding with hypercholesterolemic diet showed hypercholesterolaemia and hyperinsulinemia with modest elevation of blood glucose." (PMID 27282931, 2016).
Hyperinsulinemia (continued). "Consistent with their elevated serum insulin levels, the pancreatic sections of Ks Leprdb/db mice fed a curcumin-supplemented diet contained markedly enlarged islets with numerous Ki-67-positive β-cells similar to those observed in obese Lepob/ob B6 animals with compensatory hyperinsulinemia." (PMID 27110686, 2016). "To determine whether the effects of glucagon or epinephrine on VPK were related to the expected hyperinsulinemia following hormone treatment, we performed hyperinsulinemic-euglycemic clamps to match plasma insulin concentrations to those measured in the epinephrine- and glucagon-treated rats." (PMID 27002151, 2016). "Thus, impaired insulin function could lead to compensatory hyperinsulinemia, where the body attempts to balance the reduced effect of insulin by producing and releasing more insulin." (PMID 26924554, 2016). "The co-existence of even modest insulin sensitivity with the extreme hyperinsulinemia in the same mice is surprising, and it suggests that the yellow obese mutation on the KK genetic background may provide a unique model for elucidation of the mechanisms by which insulin regulates energy metabolism." (PMID 27922820, 2016). "Moreover, hyperinsulinemia might be additionally triggered by impaired insulin action due to decreased insulin extraction in the liver." (PMID 27505055, 2016). "This large amount of insulin release could create chronic hyperinsulinism." (PMID 27504460, 2016). "Interestingly, insulin/IGF receptor signaling has been reported to abrogate the quiescent state of stem cells, which underlines our hypothesis that hyperinsulinemia increases cell proliferation in PDA." (PMID 25885700, 2015). "Moreover, although we suggested that the hyperinsulinemia would be the possible main cause of elevated nighttime HR levels, we did not measure the plasma insulin levels." (PMID 26064992, 2015). "If hyperinsulinemia does not allow the maintenance of normoglycemia, it may cause an overexpression of insulin activity in some normally sensitive tissues." (PMID 26198245, 2015). "In addition to hypoxia, this could be due to the more severe hyperinsulinemia of obese mice, since it is known that insulin increases HIF-1α mRNA in adipocytes, or other different stimuli." (PMID 26619907, 2015). "The association between metformin and a reduced risk of cancer in diabetic patients may simply be explained through the action of metformin on the improvement in blood glucose and insulin levels because hyperinsulinemia and hyperglycemia play an important role in cancer proliferation." (PMID 25050322, 2014). "To test this hypothesis, we used cultured rat aortic smooth muscle cells line (A10) to examine the potential effect of D4 receptors on insulin-mediated proliferation and migration, and investigated the role of D4 receptors on neointimal hyperplasia in Sprague–Dawley (SD) rats with hyperinsulinemia." (PMID 24888351, 2014). "The major mechanisms by which β-cells generate hyperinsulinemia during adaptive compensation consist of functional (e.g., increased insulin biosynthesis and/or secretion) and structural adaptations (e.g., increased β-cell hyperplasia and hypertrophy that may result in increased β-cell mass)." (PMID 25313308, 2014). "Cersosimo group suggested pioglitazone preserved Akt phosphorylation and attenuates MAPK signaling in insulin-stimulated VSMCs, and may play a role in arterial smooth muscle cells migration, proliferation, and inflammation in conditions of acute hyperinsulinemia." (PMID 25302079, 2014). "Thus, at low doses, insulin exerts anti-inflammatory effects; whereas, during chronic hyperinsulinemia, insulin may exacerbate inflammatory responses and increase markers of oxidative stress." (PMID 24574966, 2014). "Therefore, like GPR40 knockout mice, DC260126 might reduce insulin tolerance mainly through decreasing hyperinsulinemia in db/db mice." (PMID 23776696, 2013).
Hyperinsulinemia (continued). "If hyperinsulinemia following an oral glucose load is an important contributor to the early decrease in plasma IL-6 concentrations then this decrease should be attenuated when circulating insulin levels are substantially lower at the same blood glucose concentrations." (PMID 23776669, 2013). "Given the role of PDX1 in β-cell replication, and elevated fetal INS expression, these alterations in expression in response to d62 MI-TP may therefore represent fetal antecedents of the increased β-cell numbers and hyperinsulinemia observed in offspring from MI-TP manipulated pregnancies." (PMID 23457541, 2013). "Although insulin has a lower affinity than the IGFs for this hybrid receptor, it could be activated by the high insulin concentrations present in insulin-resistant individuals with hyperinsulinemia in whom serum insulin concentrations can be as high as 0.8 nM." (PMID 23983688, 2013). "Furthermore, our findings support the notion that terminal arterioles rapidly respond to physiological hyperinsulinemia, and in a time scale that would facilitate both insulin/AA delivery to muscle to support muscle protein anabolic and insulin-mediated actions on glucose uptake processes." (PMID 24303186, 2013). "And it could also reduce hyperinsulinemia and improve insulin sensitivity in Zucker fatty rats." (PMID 23776696, 2013). "Thus, in the face of hyperinsulinemia in insulin-resistant conditions, the liver continues to produce glucose but also synthesizes large amounts of fatty acids and triglycerides, which accumulate in the liver, producing the pathological condition known as hepatic steatosis." (PMID 24058052, 2013). "Thus, the marked tesaglitazar induced reduction in FFA flux into skeletal muscles (at hyperinsulinemia) may explain the apparent enhancement in insulin stimulated oxidative glucose disposal in this tissue via the glucose-fatty acid cycle." (PMID 24285952, 2013). "Therefore, we hypothesized that maintenance of hyperinsulinemia during HD by either glucose or glucose-insulin infusion would suppress the HD-induced decrease in serum bioactive IGF-I as well as the increase in plasma IL-6." (PMID 23557110, 2013). "In addition to the effects of hyperinsulinemia, other insulin-independent mechanisms may participate in the pathogenesis of TPP." (PMID 23939916, 2013). "Besides hyperinsulinemia, other insulin-independent factors may also play pivotal roles in the pathogenesis of TPP." (PMID 23939916, 2013). "Furthermore, differences were observed in genes contributing to fatty acid, cholesterol and triglyceride metabolism (FATP2, ELOVL6, PNPLA3, SREBF1) and in genes involved in regulating lipolysis (ANGPTL4) between the insulin-resistant and -sensitive subjects especially during hyperinsulinemia." (PMID 22471940, 2012). "According to our current data and in consideration of recent findings in animal models, we hypothesize that hyperinsulinemia – via increased insulin signaling in osteoblasts- activates osteocalcin which in turn stimulates insulin secretion in pancreatic beta-cells." (PMID 22844418, 2012). "However, many cancer cells overexpress IGF-1 receptors, so that the interaction with insulin could become more relevant, particularly in conditions of hyperinsulinemia." (PMID 23209929, 2012). "However, it is also conceivable that development of INS resistance in conditions of overnutrition and hyperinsulinemia is actually a compensatory mechanism that may serve to protect cardiac cells from excessive signaling generated by excess INS and nutrients." (PMID 21977024, 2012). "However, the marked increase in IL-6 expression together with a clear delocalization to insulin granules questions the possible involvement of IL-6 in the hyperinsulinemia of fa/fa rats, which deserves to be reassessed in vivo in this model of prediabetic state." (PMID 21826222, 2011).
Hyperinsulinemia (continued). "The abundant evidence suggesting that IR and resultant hyperinsulinemia facilitate ovarian hyperandrogenism is central to the argument for the use of insulin sensitizers to treat adolescents with PCOS, when treatment might preclude adverse metabolic, reproductive and cardiovascular outcomes." (PMID 21899727, 2011). "Furthermore, hyperinsulinemia may ultimately upregulate the insulin mitogenic pathway compared to the insulin metabolic pathway." (PMID 21773024, 2011). "Although the glucose level only increases within 30 min after the blood injection, the plasma insulin level begins to rise continuously 30 min after the injection and reaches its maximum 5 days after the second injection, implying that CVS is associated with hyperinsulinemia." (PMID 21801458, 2011). "Thus, chronic activation of monocyte IL-6 production by high levels of fatty acids and hyperinsulinemia in insulin resistant subjects could produce local and systemic inflammation." (PMID 21054880, 2010). "Thus, in this model energy (glucose, triglycerides) is not removed from systemic circulation effectively despite elevated insulin (hyperinsulinemia reflecting insulin resistance), which leads to a blood glucose increase that eventually leads to beta-cell failure with decreased insulin production." (PMID 20398338, 2010). "Similarly, we report here that reduced insulin sensitivity and hyperinsulinemia are also evident in (F2) animals whose mothers were fed energy-restricted diets throughout pregnancy/lactation and are then maintained on the same energy restricted diet post weaning." (PMID 18928547, 2008). "Chronic hyperinsulinemia diminishes the production of hepatic SHBG and increases androgen levels via activating CYP17A1 in theca cells through insulin stimulation." (PMID 41596408, 2026). "In insulin-resistant states, impaired IRS-1/PI3K/Akt metabolic signaling triggers compensatory hyperinsulinemia." (PMID 41601879, 2026). "Second, changes in hepatic insulin clearance or transient compensatory hyperinsulinemia related to concurrent background therapies (e.g. use of insulin secretagogues or withdrawal/alteration of other agents) might increase measured fasting insulin independently of insulin sensitivity." (PMID 41450584, 2025). "In the serum insulin assessment, we found that both the HFD-fed and the WT + D2 groups exhibited hyperinsulinemia, an effect that was bot observed in the KO + D2 group." (PMID 41329353, 2025). "Research performed on hyperinsulinemia and T2DM has concluded that they are both conditions which pertain to insulin regulation—or the lack thereof." (PMID 39857716, 2025). "Crucially, it improved hyperinsulinemia by downregulating the HOMA-IR index and upregulating the ISI, indicating enhanced insulin sensitivity." (PMID 40647154, 2025). "Hyperinsulinemia, especially excessive early-phase insulin secretion, is a common prelude to T2D and MASLD and the hyper-secretion of insulin often seen in people with T2D is exasperated when MASLD co-occurs." (PMID 40502600, 2025). "Similar to HOMA-IR trajectories, fasting serum insulin, a key determinant of HOMA-IR, serves as a sensitive indicator of compensatory hyperinsulinemia, which is central to the pathophysiology of IR in PCOS." (PMID 40823908, 2025). "Obese mares exhibited hyperinsulinemia along with reduced levels of albumin, albumin/globulin ratio, IGF-1, and glucose/insulin ratio." (PMID 40901060, 2025). "Berberine activates AMPK in pancreatic β cells and regulates insulin gene transcription by inhibiting the expression of mouse insulin promoter, mRNA, and protein through the AMPK pathway, thereby playing a therapeutic role in T2DM with hyperinsulinemia." (PMID 41158622, 2025). "In the oral glucose tolerance test (OGTT), the insulin area under the curve (sigma IRI) over 120 min also showed a downward trend, particularly in patients with baseline hyperinsulinemia (sigma IRI ≥ 250 μU·hr./ml), where the decrease was more pronounced." (PMID 41018201, 2025).
Hyperinsulinemia (continued). "In contrast, 2 h insulin levels were inversely correlated with SHBG (r = −0.43, p < 0.01), reflecting the suppressive effect of hyperinsulinemia on SHBG production." (PMID 40868057, 2025). "The median fasting insulin concentrations increased by 2.82 μU/ml per 2-year NHANES cycle, while the prevalence rates of hyperinsulinemia and IR increased by 3.35% and 3.41% (relative increase) per 2-year NHANES cycle, respectively." (PMID 40365140, 2025). "Consistent with this, plasma insulin levels at week 16 were significantly higher in both control and PKDkd-EGFP mice on HFD compared with LFD-fed mice, reflecting hyperinsulinemia, however, the increase was less pronounced in PKDkd-EGFP mice." (PMID 41349796, 2025). "IR is characterized by an abnormal cellular response to insulin, manifested as elevated NEFA, impaired blood glucose regulation, and hyperinsulinemia, indicative of metabolic dysfunction." (PMID 40428201, 2025). "Insulin and LH act synergistically to enhance androgen biosynthesis, while the reduction of SHBG by hyperinsulinemia amplifies circulating free androgens." (PMID 41155686, 2025). "Insulin pretreatment essentially abrogated the ability of IGF1 to regulate Atf4, Agrp, and Pomc, suggesting that hyperinsulinemia induced IGF1 resistance in hypothalamic neurons." (PMID 40105689, 2025). "Common after RYGB postprandial hypoglycemia results from hyperinsulinemia driven by glucagon-like peptide 1 (GLP-1) and reduced insulin clearance." (PMID 40005017, 2025). "T2DM disrupts normal ovarian function since IR and hyperinsulinemia trigger the overproduction of IGF-1 and overexpression of hybrid insulin/IGF-1 receptors." (PMID 38353886, 2024). "Since acute stimulation with insulin inhibited IFNγ production in CD4+ cells, we asked if chronic hyperinsulinemia mirrored this effect." (PMID 39768214, 2024). "VAT induces hyperinsulinemia by the secretion of IGFBP1 and 2, increases free insulin and IGF-1, stimulates cell proliferation, inhibits apoptosis, and favors angiogenesis." (PMID 38785834, 2024). "Prolonged hyperinsulinemia leads to the downregulation of insulin receptors at the BBB, decreasing insulin transport into the brain." (PMID 39596023, 2024). "The exact significance of hyperinsulinemia in pediatric patients is controversial, although it is a well-validated cardiovascular risk factor: in fact, several studies have highlighted that increased insulin secretion is not necessarily associated with weight gain or worsening BMI over time." (PMID 38920551, 2024). "Not only relative hyperinsulinemia but also oxidants, such as NO, attack the IDE, which ultimately loses its proteolysis function towards insulin and Aβ." (PMID 39767690, 2024). "For example, in the fasting (low insulin) state, FOXA2 activates transcriptional programs of lipid metabolism and ketogenesis, whereas, in hyperinsulinemia, FOXA2 is inactivated, thereby promoting hepatic lipid accumulation and insulin resistance." (PMID 38605023, 2024). "Six weeks of essential oil treatment reduced the insulin response to the OST (i.e., delta between 60 and 0 min) in horses with severe initial hyperinsulinemia (treatment*covariate p = 0.008)." (PMID 39687851, 2024). "As we advance in our understanding of the intricate interplay between insulin dysregulation and neddylation in cancer progression, careful evaluation of neddylation inhibitors in cancer patients with T2DM or hyperinsulinemia is necessary." (PMID 38272982, 2024). "Due to the inability to immediately lower insulin levels at the onset of EXE, individuals with T1DM often experience hyperinsulinemia during PA." (PMID 38542818, 2024). "Insulin typically exerts inhibitory effects on PLT aggregation; thus, hyperinsulinemia, as observed in our study, can contribute to PLT hypercoagulation and hyperactivation." (PMID 39858414, 2024).